DGCR8 (DGCR8 microprocessor complex subunit)
Diseases named in the same sentence as DGCR8 in open-access papers (continued):
Sharing a sentence is not in itself a finding about the gene and the disease.
COVID-19 (2 papers, 2021 to 2023). A disease caused by infection with severe acute respiratory syndrome coronavirus 2. "Dicer, Drosha, Ago2, and DGCR8 are essential components of the RNAi system, which is supposed to be dysregulated in COVID-19 patients." (PMID 34715923, 2021). "Dicer, Drosha, Ago2, and DGCR8 (critical components of RNAi) were selected for evaluation in COVID-19 patients." (PMID 34715923, 2021). "mRNA levels of AGO2, DICER1, DGCR8, DROSHA, and Exportin-5 (XPO5) were measured by quantitative reverse-transcription polymerase chain reaction (RT-qPCR) in nasopharyngeal swab specimens from patients with COVID-19 and controls, as well as in cells infected with SARS-CoV-2 in vitro." (PMID 37243263, 2023). "Our data showed that the mRNA expression levels of AGO2, DICER1, DGCR8, DROSHA, and XPO5 were not significantly different in patients with severe COVID-19 when compared to patients with non-severe COVID-19 and controls." (PMID 37243263, 2023). "Measured mRNA levels of AGO2, DICER1, DGCR8, DROSHA, and XPO5 were not significantly different in nasopharyngeal swab specimens of severe COVID-19 patients compared to non-severe COVID-19 patients or controls." (PMID 37243263, 2023).
endometriosis (2 papers, 2023 to 2025). The growth of functional endometrial tissue in anatomic sites outside the uterine body. "Our goal, therefore, was to evaluate whether the gene expressions of DROSHA, DGCR8, XPO5, DICER, and AGO1 to AGO4 are differential in MenSCs of women with endometriosis." (PMID 36983035, 2023).
glaucoma (2 papers, 2023 to 2025). Increased pressure in the eyeball due to obstruction of the outflow of aqueous humor. "But we cannot completely rule out the role of different polymorphisms in these or other genes (e.g., DGCR8, XPO5) significant to the miRNA biogenesis pathway in glaucoma." (PMID 37099569, 2023).
head and neck cancer (2 papers, 2012 to 2015). A primary or metastatic malignant neoplasm affecting the head and neck. "Because of the direct effect of DGCR8 and RNASEN on miRNA biogenesis and the associations between miRNA expression and cancer development the variations in either gene might affect head and neck cancer occurrence." (PMID 26688807, 2015).
hydronephrosis (2 papers, 2015 to 2020). Collection of urine in the renal pelvis that results in dilatation of the renal pelvis and calyces. "In this study we show that loss of Dgcr8 dependent miRNAs in the kidney epithelium leads to severe hydronephrosis, kidney cysts and rapid kidney failure." (PMID 25881298, 2015). "Further examination of the kidneys of the Dgcr8 knockout mice showed the macroscopic picture of severe hydronephrosis with a dilated ureter and kidney pelvis." (PMID 25881298, 2015).
hypothyroidism (2 papers, 2016 to 2022). Abnormally low levels of thyroid hormone. "Dgcr8 fl/fl; Pax8Cre+ knockout mice died prematurely, developed massive hypothyroidism and end stage renal disease due to a loss of miRNAs in Pax8 expressing tissue." (PMID 27090781, 2016). "The conditional knock-out of DGCR8 at early stages of thyroid development leads to severe hypothyroidism with almost undetectable free thyroxine, thyroid tissue disorganization and few follicular structures." (PMID 36499151, 2022). "Analysis of free thyroxine (fT4) revealed massive hypothyroidism in Dgcr8 knockout mice since essentially almost no fT4 was detectable anymore." (PMID 27090781, 2016). "We can thus speculate that, differently to what observed in Dicer knockout mice, the hypothyroidism observed in Dgcr8 knockout mice does not depend on a block of differentiation, as the differentiation markers Tg and Nis are expressed in the residual follicles." (PMID 27090781, 2016).
liver cancer (2 papers, 2020 to 2025). An epithelial or non-epithelial malignant neoplasm that arises from the liver. "In liver cancer, multiple different groups’ investigations showed that METTL14 inhibits EMT, invasion and metastasis of liver cancer cells by regulating m6A-modified target mRNAs such as EGFR/PI3K/AKT, DGCR8/primiR-126, USP48/SIRT6/glycolysis, CSAD, GOT2 and SOCS2." (PMID 40734692, 2025).
lung adenocarcinoma (2 papers, 2009 to 2023). A carcinoma that arises from the lung and is characterized by the presence of malignant glandular epithelial cells. "Experimental knockdown of miRNA processing factors, such as DiGeorge syndrome critical region 8 (DGCR8), Drosha, or Dicer in mouse lung adenocarcinoma cells dramatically elevates properties of tumorigenesis, including proliferation, soft agar colony formation, and in vivo tumor burden." (PMID 19664273, 2009).
microcephaly (2 papers, 2021). A congenital or acquired developmental disorder in which the circumference of the head is smaller than normal for the person's age and sex. "DGCR8 is an essential component of the microRNA processing complex involved in the biogenesis of microRNA, and another work indicates that knockout DGCR8 could induce microcephaly." (PMID 34073122, 2021).
multinodular goiter (2 papers, 2024). Nodular goiter characterized by more than one discrete tissue mass. "Notably, DGCR8 p.E518K missense mutations, which disrupt microRNA processing and are linked to familial multinodular goiter, were found in two cases." (PMID 39061714, 2024).
nasopharyngeal carcinoma (2 papers, 2020 to 2025). A carcinoma arising from the nasopharyngeal epithelium. "CircCCNB1 expression is down‐regulated in nasopharyngeal carcinoma (NPC); thus, less NF90 protein is bound to circCCNB1 and more binds to pri‐miRNAs, blocking their (pri‐miRNAs) binding to DGCR8 and inhibiting the processing and generation of miR‐15b‐5p/miR‐7‐1‐3p." (PMID 39964093, 2025).
schwannoma (2 papers, 2022 to 2023). A benign, usually encapsulated slow growing tumor composed of Schwann cells. "However, many patients and families with schwannomatosis do not have identifiable germline variants in NF2, SMARCB1, LZTR1, CDKN2A, or DGCR8, and efforts have been underway to identify other responsible molecular drivers of schwannoma predisposition." (PMID 37821623, 2023).
ZIKV infection (2 papers, 2017 to 2019). "Similarly, ZIKV infection in HepG2 cells led to a decrease in DGCR8, Ago1, and Ago3 expression." (PMID 30781519, 2019).
acute myeloid leukemia (1 paper, 2017). Acute myeloid leukemia (AML) is a group of neoplasms arising from precursor cells committed to the myeloid cell-line differentiation. "HDAC1 enhances miRNA processing by acetylating protein DGCR8 (DiGeorge critical region 8 protein) which processes miRNA and this acetylation increases the production of mature miRNAs in embryonic kidney cells and acute myeloid leukemia cells (AML)." (PMID 28671573, 2017).
adenoma (1 paper, 2013). A neoplasm arising from the epithelium. "Here, we evaluated the mRNA expression of DROSHA, DGCR8, DICER (DICER1), TARBP2, and PRKRA, the core components in the miRNA biogenesis pathway, in a cohort of 73 adrenocortical tumors (including 43 adenomas and 30 carcinomas) and nine normal adrenal cortices using a RT-qPCR approach." (PMID 23671264, 2013).
adrenocortical tumors (1 paper, 2013). "We analyzed the mRNA expression levels of five miRNA-processing genes (DROSHA, DGCR8, DICER, TARBP2, and PRKRA) in 73 adrenocortical tumors and nine adrenal cortices using RT-qPCR." (PMID 23671264, 2013).
adult T cell Leukemia (1 paper, 2023). "Interestingly, the authors measured DROSHA, DGCR8, XPO5, DICER1, AGO2, and AGO3 mRNA expression, and only DICER1 mRNA was differently expressed in CD8+ T-cell–depleted PBMCs from HTLV-1 asymptomatic carriers when compared to patients with acute adult T cell Leukemia." (PMID 37243263, 2023).
alcohol dependence (1 paper, 2023). Physical and psychological dependence on alcohol. "Moreover, Gedik reported a genetic association of DGCR8, AGO1, and AGO2 alleles with alcohol dependence risk." (PMID 38116240, 2023).
Alzheimer disease (1 paper, 2022). A progressive, neurodegenerative disease characterized by loss of function and death of nerve cells in several areas of the brain leading to loss of cognitive function such as memory and language. "Interestingly, three of these genes (EPN2, SNX15, and DGCR8) have previously been associated with hippocampal functioning and processes linked to the development of Alzheimer’s disease (AD)." (PMID 35933470, 2022).
aneurysm (1 paper, 2025). Bulging or ballooning in an area of an artery secondary to arterial wall weakening. "In the context of aneurysms, similar to how METTL14 promotes DGCR8-mediated processing of pri-miR-19a in atherosclerosis, METTL3-dependent m6A methylation promotes primary miR-34a maturation through DGCR8, leading to decreased SIRT1 expression and an aggravated aneurysm formation." (PMID 40005339, 2025).
ankylosing spondylitis (1 paper, 2017). An autoimmune chronic inflammatory disorder characterized by inflammation in the vertebral joints of the spine and sacroiliac joints. "Fold changes of Drosha, Dicer, and DGCR8 expressions in patients with ankylosing spondylitis (AS) in comparison to healthy subjects (HS)." (PMID 32185262, 2017).
autoimmune disease (1 paper, 2025). A disorder resulting from loss of function or tissue destruction of an organ or multiple organs, arising from humoral or cellular immune responses of the individual to their own tissue constituents. "Low expressions of Drosha, DGCR8, and Dicer may reduce certain miRNAs, such as miR-27b, miR-let7f, miR-21, and miR-98, which are associated with the immune system or autoimmune diseases." (PMID 40837640, 2025).
cardiac failure (1 paper, 2017). "Cardiomyocyte-specific deletion of Dgcr8+/− demonstrated downregulation of a subset of mature cardiac enriched miRNAs; these mice experienced premature lethality due to cardiac failure, pointing out a critical role for miRNAs in maintaining cardiac function in mature cardiomyocytes." (PMID 28507561, 2017).
cutaneous melanoma (1 paper, 2024). A primary melanoma arising from atypical melanocytes in the skin. "The second most recurrently altered TAD boundary in our cutaneous melanoma cohort affected the NER genes HIRA and DGCR8, which are involved in the repair of mutations caused by UV mutagenesis." (PMID 38758740, 2024).
cyst (1 paper, 2019). A sac-like closed membranous structure that may be empty or contain fluid or amorphous material. "While cystic EBs were observed for wild type cells at day 8 and day 16, EBs from both Dgcr8 knockout and Dgcr8/pri-miR-290~295 double knockout cells failed to form a cyst, suggesting incomplete differentiation." (PMID 31491855, 2019).
embryonic carcinoma (1 paper, 2025). "To validate this prediction, we generated H9 hESCs and human embryonic carcinoma cells (PA-1 hECCs), where a single copy of the DGCR8 gene was inactivated using the CRISPR/Cas9 nickase system." (PMID 40138719, 2025).
end stage renal disease (1 paper, 2015). "None of the Dgcr8 knockout mice analyzed so far survived longer than 8 weeks, most likely due to development of end stage renal disease." (PMID 25881298, 2015).
esophageal squamous cell carcinoma (1 paper, 2025). Esophageal squamous cell carcinoma (ESCC) is a type of esophageal carcinoma (EC) that can affect any part of the esophagus, but is usually located in the upper or middle third. "For instance, in esophageal squamous cell carcinoma (ESCC), METTL14 upregulates miR-99a-5p by modulating the processing of m6A-mediated DGCR8-dependent pri-miR-99a." (PMID 40161350, 2025).
esophagitis (1 paper, 2016). An acute or chronic inflammatory disease affecting the esophageal wall. "After multiple comparison correction, RPS6KB2:rs10274, SMO:rs1061280, SMO:rs1061285 remained significantly associated with esophagitis, while processing gene DGCR8:rs720014, DGCR8:rs3757, DGCR8:rs1633445 remained significantly associated with pneumonitis." (PMID 26991123, 2016).
fragile X syndrome (1 paper, 2024). A genetic syndrome caused by mutations in the FMR1 gene which is responsible for the expression of the fragile X mental retardation 1 protein. "It has been shown that DGCR8 binds preferentially to expansion of CGG repeats in the 5′ UTR of FMR1 gene, thus showing a link between miRNAs regulation, Fragile X Syndrome, and vascular development." (PMID 39654947, 2024).
fragile X-associated tremor/ataxia syndrome (1 paper, 2022). Fragile X-associated tremor/ataxia syndrome (FXTAS) is a rare neurodegenerative disorder characterized by adult-onset progressive intention tremor and gait ataxia. "For instance, the expanded CGG repeats in FMRP (causing Fragile X-associated tremor/ataxia syndrome) sequester DGCR8 and Drosha and disrupt miRNA maturation in mice." (PMID 35869509, 2022).
head and neck squamous cell carcinoma (1 paper, 2023). A squamous cell carcinoma that arises from any of the following anatomic sites: lip and oral cavity, nasal cavity, paranasal sinuses, pharynx, larynx, and salivary glands. "Nevertheless, two recent studies have indicated that DGCR8 enhances radiosensitive of head and neck squamous cell carcinoma." (PMID 36811004, 2023).
intrahepatic cholangiocarcinoma (1 paper, 2023). A carcinoma that arises from the intrahepatic bile duct epithelium in any site of the intrahepatic biliary tree. "have demonstrated that METTL3 promoted apoptosis, autophagy, and pyroptosis of glutamic acid-induced intrahepatic cholangiocarcinoma (ICC) by interacting with DGCR8 and modulating the miR-30b-5p/PIK3R2 axis in an m6A-dependent manner." (PMID 37182154, 2023).
larynx cancer (1 paper, 2015). A primary or metastatic malignant neoplasm involving the larynx. "In turn, the rs14035 RAN CT heterozygote and DGCR8 rs417309 GG genotype were significantly inversely associated with the presence of larynx cancer." (PMID 26688807, 2015). "In our study we evaluated the role of three DGCR8 SNPs in larynx cancer: rs3757, rs417309, and rs1640299." (PMID 26688807, 2015). "This is the first report considering the association of the risk of larynx cancer and SNPs of the following polymorphisms: DROSHA (rs6877842), DGCR8 (rs3757, rs417309, and rs1640299), RAN (rs14035), XPO5 (rs11077), DICER1 (rs13078 and rs3742330), and TARBP2 (rs784567)." (PMID 26688807, 2015).
lymph node metastasis (1 paper, 2023). "Mutation of DGCR8 gene showed a significant association with lymph node metastasis (OR = 1.80, 95% CI = 1.02–3.17, p = 0.041), high tumor size (OR = 2.73, 95% CI = 1.45–5.13, p = 0.002), and distant metastasis (OR = 2.45, 95% CI = 1.03–5.85, p = 0.043)." (PMID 36672288, 2023). "Patients with DGCR8, DROSHA, and TARBP2 mutations were twice as likely to present with lymph node metastasis." (PMID 36672288, 2023).
male infertility (1 paper, 2014). The inability of the male to effect fertilization of an ovum after a specified period of unprotected intercourse. "The results indicate that germ cell-specific deletion of Dicer1 or Dgcr8 resulted in reduced testis size and sperm count, and male infertility." (PMID 25244517, 2014).
myeloma (1 paper, 2022). "Using immunofluorescent staining, we observed a co-localization of hnRNPA2B1 and DGCR8 in myeloma cells." (PMID 36451863, 2022). "We immunoprecipitated myeloma cells lysates with an anti-DGCR8 antibody and observed the presence of hnRNPA2B1 proteins in the lysates." (PMID 36451863, 2022).
non-small cell lung carcinoma (1 paper, 2023). A group of at least three distinct histological types of lung cancer, including non-small cell squamous cell carcinoma, adenocarcinoma, and large cell carcinoma. "LINC01234 interacts with HNRNPA2B1, leading to the recruitment of DGCR8 and promoting the processing and maturation of miR-106b-5p, which inhibits CRY2 and promotes the growth of non-small cell lung cancer (NSCLC) cells." (PMID 37178254, 2023).
osteoarthritis (1 paper, 2019). A noninflammatory degenerative joint disease occurring chiefly in older persons, characterized by degeneration of the articular cartilage, hypertrophy of bone at the margins and changes in the synovial membrane. "Meanwhile, the rescue effect of DGCR8 on osteoarthritis was further evaluated in physiologically aged mice." (PMID 31350386, 2019). "Accordingly, we proposed that the ectopic expression of DGCR8 may attenuate the development of osteoarthritis by repressing cellular senescence." (PMID 31350386, 2019). "Finally, DGCR8 was downregulated in pathologically and naturally aged hMSCs, whereas DGCR8 overexpression alleviated hMSC aging and mouse osteoarthritis." (PMID 31350386, 2019). "Moreover, a decrease in DGCR8 level was detected in hMSCs from older individuals, and restoring level of wildtype DGCR8 (or a miRNA-irrelevant version of DGCR8) attenuated hMSC senescence, as well as post-traumatic articular aging and osteoarthritis in mice." (PMID 31350386, 2019).
pneumonitis (1 paper, 2016). An inflammatory process affecting the lung parenchyma. "Patients with the GG+GA genotype of DGCR8:rs720014 had a 3.54-fold increased risk of pneumonitis (OR: 3.54, 95% CI: 1.65–7.61, p <0.05, q <0.1)." (PMID 26991123, 2016). "Gene-based analysis showed DGCR8 (p = 0.010) and GEMIN4 (p = 0.039) were the top genes associated with the risk of developing pneumonitis." (PMID 26991123, 2016). "We observed that DGCR8 (p value: 0.010) and GEMIN4 (p value: 0.039) were significantly associated with pneumonitis, while XPO5 reached borderline significance (P = 0.087)." (PMID 26991123, 2016). "Our results show that three SNPs in the DGCR8 gene are among the top SNPs identified in pneumonitis, and gene-based analysis showed that the DGCR8 gene is the most significant gene in the analysis of pneumonitis (P = 0.010)." (PMID 26991123, 2016). "Gene based analysis supported a significant role of DGCR8 and GEMIN4 in the risk of pneumonitis." (PMID 26991123, 2016). "Daniel Gomez-Cabello found that DGCR8 may participate in pneumonitis through affecting fibroblasts ‘cell proliferation." (PMID 26991123, 2016).
preeclampsia (1 paper, 2019). Preeclampsia is a hypertensive disorder of pregnancy that is characterized by new-onset hypertension with proteinuria presenting after 20 weeks of gestation, and depending on mild or severe forms may initially present with severe headache, visual disturbances, and hyperreflexia. "Our studies confirmed that polymorphisms in DGCR8 might participate in the pathological process of preeclampsia." (PMID 31484500, 2019). "Polymorphisms in DGCR8 might participate in the pathological process of preeclampsia." (PMID 31484500, 2019). "However, the impact of polymorphisms in DGCR8 which is indispensable in miRNA maturing processing on the susceptibility to preeclampsia (PE) has not been elucidated yet." (PMID 31484500, 2019).
rhabdoid tumor (1 paper, 2023). An aggressive malignant embryonal neoplasm usually occurring during childhood. "For instance, atypical deletions could involve the tumor suppressor gene SMARCB1 (MIM_609322), which is associated with rhabdoid tumors, or DGCR8 gene (MIM_609030), which has been found to result in aberrant levels of miRNA leading to an increased susceptibility to malignancies." (PMID 37635986, 2023).
s sarcoma- (1 paper, 2018). "miR-SNPs in miR-125a and Kaposi’s sarcoma-associated herpes virus-encoded miR-K5 were reported to impair miRNA processing by the Drosha/DGCR8 complex." (PMID 29997453, 2018).
scoliosis (1 paper, 2022). A congenital or acquired spinal deformity characterized by lateral curvature of the spine. "Further suggestions for a common miRNA expression alteration link between 22q11DS and AIS were derived from observations of the involvement of DGCR8 in bone turnover, the impairment of which is strongly involved in scoliosis." (PMID 36422101, 2022). "The DGCR8 gene seems to be essential for microRNA biogenesis, which is why we propose that a possible common pathological mechanism between scoliosis and 22q11.2DS could be the dysregulation of microRNA expression." (PMID 36422101, 2022).